IL4 (interleukin 4)
Diseases named in the same sentence as IL4 in open-access papers (continued):
Sharing a sentence is not in itself a finding about the gene and the disease.
asthma (continued). "Furthermore, as predicted from our earlier work, cells from the calcitriol-treated patients with SR asthma now showed a significant increase in IL-10 production in response to dexamethasone, an effect that was most marked in the presence of IL-4 in culture." (PMID 25772594, 2015). "Importantly, we show that β-CAT-Tg iNKT cells acquired the ability to produce enhanced levels of IL-4 and IL-13 during development that augmented lung inflammation in a mouse model for asthma." (PMID 26482437, 2015). "DA could dose-dependently inhibited ovalbumin-induced increases in total and eosinophil counts, IL-4, IL-5, and IL-13 levels in lavage fluid in a mouse asthma model." (PMID 26223251, 2015). "Irrespective of the exposure or disease status, methylation of several asthma and allergy-related genes changed over time (IL-4, IL-13, ORMDL3, RAD50), indicating their involvement in developmental processes, while Treg-related genes (FOXP3, RUNX3) remained unchanged." (PMID 26052354, 2015). "We hypothesized that airway exposure to HDM allergen would induce or elevate the expression profile of IL-4 and IL-13 during the allergic airway response in this large animal model of asthma." (PMID 26362930, 2015). "Therefore, biologic targeted therapies have been developed to target the specific molecular pathways to treat asthma, especially those targets at IL-4, IL-5, IL-13, and IgE." (PMID 26064160, 2015). "Some studies also supported the importance of IL-4 for childhood asthma." (PMID 26000027, 2015). "The sex differences in IFN-γ production by CD8+ T cells and IFN-γ receptor expression on CD4+ T cells may be a necessary and sufficient for female-dominant IL-4 production in asthma." (PMID 26488300, 2015). "And the serum IL-4 level may be elevated in concern with decreased IFN-γ level in patients with asthma." (PMID 26000027, 2015). "Therefore, in the present study, we aimed to determine the role that CD8+ T cells play in female-dominant IL-4 production in adult asthma using a mouse model." (PMID 26488300, 2015). "The elevated IL-4 and IL-13 levels seen in the present study reinforces the idea that Th2 lymphocytes are key cellular players in directing the early immune response to allergen re-exposure in the sheep asthma model." (PMID 26362930, 2015). "Two trials were included in our meta-analysis of acupoint application for childhood asthma on IL-4." (PMID 26000027, 2015). "To clarify whether Batf-mediated IL-4 expression in Tfh cells is involved in triggering asthmatic symptoms, we used an adoptive transfer model of asthma." (PMID 26278622, 2015). "In sera, the levels of IgE and IL-4 were significantly higher in asthma mice than in control mice; the levels of IFN-γ were significantly lower in all treatment groups than in control mice; and the levels of IL-10 were significantly higher in the OVA+rAdV-CTLA4Ig DCs mice than in the other groups." (PMID 25860995, 2015). "Moreover, In vivo chronic exposure of rats to benzopyrene resulted in over expression of IL-4, the pattern that coincided the one observed in asthma group." (PMID 24450480, 2014). "However, STAT6-21*TT is overrepresented in asthmatics with a ≥10 mm wheal size reaction to storage mites and shows a significant epistatic interaction with IL4-590C/T between moderate-severe persistent and intermittent asthma." (PMID 25299150, 2014). "Th1 cells are characterized by the production of proinflammatory interferon γ (IFN-γ) to mediate cellular immunity, whereas Th2 cells produce interleukin-4 (IL-4), IL-5, and IL-13, and are responsible for regulating humoral immunity and, in pathological conditions, asthma and allergy." (PMID 24508458, 2014). "Asthma is one of the airway hyperresponsive diseases which can be characterized by the accumulation of inflammatory cells, increase in mucus production, release of certain Th2 cytokines, IL-4, IL-5, and IL-13, and increased levels of IgE." (PMID 24936861, 2014).
asthma (continued). "The elevated serum levels of IL-4, an essential cofactor for immunoglobulin E (IgE) production, and IL-5, responsible for the final differentiation, activation and recruitment of eosinophils, have been found in patients with asthma." (PMID 24450480, 2014). "Additionally, PAH administration in rodents resulted in an increased IL-4 mRNA which is supposed to partly mediate the inflammatory response noted in asthma." (PMID 24450480, 2014). "In addition, the serum expression levels of IL-4, as detected by ELISA, in the asthma and control-IgG groups were significantly higher when compared with the control group." (PMID 25289030, 2014). "Additionally, intrinsic asthma denoted by normal IgE and IL-4 levels, is associated with increased eosinophilia and IL-5 levels, compared to those with extrinsic asthma characterized by increased IL-5 and IL-4." (PMID 24971469, 2014). "Among them, Eos together with Th2 cytokines IL-4, IL-5, and IL-13 may ultimately contribute to AHR in asthma; it can also cause airway inflammation in the initial and effector phase stages of allergy." (PMID 25101137, 2014). "Total-immunoglobulin (Ig) E (tIgE), specific IgE (sIgE), and specific IgG1 (sIgG1) together with Interferon-γ (INF-γ, a Th1 cytokine) and interleukin-4 (IL-4, a Th2 cytokine) were assayed to verify at the molecular level the establishment of a rat asthma model." (PMID 24589727, 2014). "Thus, compared to non-asthma control subjects significant increase in level of IgE (123.1 ± 5.0 vs. 61.1 ± 4.3, p = 0.004), resistin (24.5 ± 1.6 vs. 17.3 ± 1.3, p = 0.001) and IL-4 (18.5 ± 3.6 vs. 9.2 ± 1.4, p = 0.003) pg ml-1." (PMID 23286340, 2013). "Pinelliae rhizome and Citrus reticulata and their combinational prescription have deep inhibitory effects on airway inflammation in a murine model of asthma and it was mediated by suppression of Th2 cytokines (IL-4, IL-5, IL-13), IgE, eosinophil CCR3 expression in lung." (PMID 24367979, 2013). "Finally, a clinically-proven anti-IgE monoclonal antibody Omalizumab abrogated the IgE-induced mediators of asthma relevance such as IL-4, IL-6, IL-8, and TNF." (PMID 24499258, 2013). "In addition, Th2 lymphocytes play important role in initiation and progression of allergic diseases such as asthma through their ability to release interleukin (IL)-4 and IL-5." (PMID 23837463, 2013). "IL-4 induces class switching and release of IgE by B cells, and IL-5 plays an important role in the induction of the eosinophil influx into the lungs in allergen-driven models of asthma." (PMID 23451035, 2013). "Thus IgE, resistin and IL-4 were significantly increased (p 0.004, 0.001 and 0.003, respectively) in children with asthma compared with non-asthma control subjects." (PMID 23286340, 2013). "Moreover, in the first large pharmacogenetic, placebo-controlled investigation of the IL-4/IL-13 pathway, three doses (1 mg, 3 mg, or 10 mg twice daily for 12 weeks) of inhaled pitrakinra were tested in patients with moderate-to-severe asthma." (PMID 23853765, 2013). "Interestingly, simultaneous exposure to inhaled diesel particles and allergen were found to induce hypomethylation within a CpG−408 site of the IL4 gene promoter in vivo correlating to IgE production putting forward a new model for the aetiology of asthma." (PMID 23641254, 2013). "In murine models of allergen-induced asthma, blockade of either IL-4 or its receptor has been shown to inhibit eosinophil influx into the airways and IL-5 release from T cells, as well as decreasing lung inflammation, serum IgE levels, and airway hyperresponsiveness to methacholine." (PMID 23853765, 2013). "As a result, STAT6 gene expression is increased and asthma is induced via an IL-4/IL-13 pathway." (PMID 23861779, 2013). "Interestingly, inhibition of different RTKs and particularly c-Kit seems to affect asthma, via decreasing histamine levels, infiltration of mast cells and eosinophils, interleukin-4 production and airway hyper-responsiveness." (PMID 24009080, 2013).
asthma (continued). "Several reports have demonstrated that TH2-type cytokines, including IL-4 and IL-13, enhance IL-17–induced release of IL-6 from fibroblasts, suggesting that IL-17 might be involved in asthma, which is a TH2-mediated disease." (PMID 22203879, 2012). "In asthma, eosinophil recruitment has been characterized by early phase IgE-mediated activation of mast cells, the production of pro-inflammatory cytokines (e.g.: IL-2, IL-4, IL-5, GM-CSF) and the late phase recruitment of Th2 cells and eosinophils." (PMID 22251275, 2012). "Using an allergic mouse model of asthma, we previously demonstrated a benefit of statins in reducing peribronchiolar eosinophilic inflammation, airway hyperreactivity, goblet cell hyperplasia, and lung IL-4 and IL-13 production." (PMID 22583375, 2012). "Our study showed higher basal IL-2 and IL-4 production in PBMCs from severe asthma which could result in p38MAPK activation and subsequent loss of corticosteroid sensitivity." (PMID 22911818, 2012). "The elevated level of IL-10 in the serum of asthma subjects indicated an increase in Type-2 activity through which the production of IL-4 and IL-13 may promote an isotype switch to IgE." (PMID 23226977, 2012). "Although IL-13 and IL-4 are both central Th2 cytokines in the immune system and potent activators of inflammatory responses and fibrosis during Th2 inflammation, recent studies demonstrated that these cytokines exerted a distinct role in asthma pathology." (PMID 22414623, 2012). "We hypothesized that maternal exposure to airborne PAH may induce altered methylation status of the asthma genes IL4 and IFNγ." (PMID 22562770, 2012). "OVA-treated mice showed significantly increased levels of IL-4 and IL-5 in both asthma models." (PMID 23189147, 2012). "Indeed, chronically activated memory T cells are observed in asthma, with an enhanced capacity to produce IL-4 and IFN-γ." (PMID 23043798, 2012). "Therapeutical interventions in allergic diseases such as allergen-induced asthma specifically targeting IL-4, IL-5 or IL-13 cytokines caused none to moderate improvement regarding disease severity and symptoms." (PMID 22853438, 2012). "Therefore, Th2 cells are important primarily in the airways, and Th2 cytokines such as interleukin (IL)-4, IL-5, and IL-13 play pivotal roles in the pathophysiology of asthma." (PMID 23244755, 2012). "These proinflammatory effects of IL-4 could, however, be downregulated by soluble IL-4 receptors, and soluble IL-4 receptors have been used to treat asthma." (PMID 22577403, 2012). "IL-4, one of key Th2-type cytokines, is highly relevant to the pathogenesis of asthma." (PMID 21939519, 2011). "Although the replication control cohort was composed of adult asthmatic and non-asthmatic subjects, IL4 SNPs were significantly associated with asthma." (PMID 21387019, 2011). "This study evaluated 8 of these genes (IL4, IL13, TNF-α, HLA-DRB1, HLA-DQB1, FCER1B/MS4A2, CD14, ADAM33) as well as 3 glutathione-s-transferase genes (GSTM1, GSTP1, and GSTT1) for association with asthma/allergy among urban-residing African Americans." (PMID 21320344, 2011). "Besides, some studies have suggested the probable contribution to asthma pathogenesis of CD8+ T-cells producing IL4 and IL5 (type 2 CD8+ T-cells) in the lungs and blood of asthmatic individuals." (PMID 22047167, 2011). "Notably IL4 SNPs rs2227284 and rs2227282 increased the odds of asthma in Caucasian children by 5.2 (95% CI 2.68–10.0 p = 1.04E-06)." (PMID 21387019, 2011). "Similarly, in the African American population, the odds of asthma for IL4 SNP rs2243250 increased from 1.75 (95% CI 1.16–2.70) in the discovery analysis to 2.15 in the replication analysis." (PMID 21387019, 2011). "Therefore, we submitted Cerk-/- mice to an ovalbumin-induced asthma model, where cytokines such as IL-4 and IL-13 are playing key roles." (PMID 20053284, 2010).
asthma (continued). "The potential of Th2 cells to promote allergic immunopathology is amplified by production of a range of mediators including IL-4, IL-5, IL-9, IL-13 and IL-25 which together promote the salient feature of asthma such as IgE production, AHR, inflammation and tissue remodelling." (PMID 19769993, 2010). "Among these genes, one SNP in IL4 that has been associated with asthma (rs2070874, +33C/T) has also been genotyped in the HGDP-CEPH panel; again, the allele that positively correlates with helminth diversity (T) is associated with asthma." (PMID 20807397, 2010). "The early induction of IL-4-producing antigen-specific T cells in the first few weeks of immunotherapy would fit with observations of late asthmatic reactions in individuals receiving peptide immunotherapy for cat allergen reactive asthma." (PMID 20543955, 2010). "Inflammatory mediator release including Th2 cytokines (IL-4 and IL-13), and lipid eicosanoids (prostaglandins, leukotrienes and lipoxins), from eosinophils also contribute to the clinical symptoms of asthma through their potent effects on airway vascular tissue and smooth muscle reactivity." (PMID 19769993, 2010). "It has been shown that IL-4, IL-5 and IL-13, the well-defined Th2 cytokines, play an important role in the pathophysiology of allergic diseases including asthma These Th2 cytokines were significantly decreased in CC10-Smad7 mice compared to the wild type animals." (PMID 20405019, 2010). "To test our hypothesis we measured serum concentrations of eleven cytokines and chemokines that were recently described to play an important role in asthma pathogenesis: IL-4, IL-5, IL-8, IL-10, IL-12 (p40), IL-13, IL-17, TNFα, GM-CSF, eotaxin, and IFNγ." (PMID 21179211, 2010). "Frequencies of CD4+ and CD8+ T cells producing IL-4, IL-13 after in vitro stimulation were significantly higher in asthma patients than in the control group (IL-4: P < .00001, P < .00003 for CD4+ and CD8+ T cells, resp., IL-13: P < .00001 for CD4+ and CD8+ T cells)." (PMID 21197090, 2010). "The importance of these factors has further been figured out in mouse models of experimental asthma: neither in animals deficient for IL-4 or IL-13 nor in animals deficient for the IL-5 receptor it was possible to induce allergic airway inflammation or AHR." (PMID 20976014, 2010). "For IL4, imputation suggested rs2070874 (C-33T) to be significantly associated with asthma (p = 0.005) but the association was not significant when re-genotyped by matrix-assisted laser desorption/ionization time-of flight (MALDI-TOF) (p = 0.054)." (PMID 21103062, 2010). "In addition, previous studies have shown that corticosteroids can suppress IL-4 and IL-5 release from peripheral blood cells of asthma patients in vitro and in vivo." (PMID 19436703, 2009). "Both Il-4 and IL-13 are cytokines associated with the inflammatory process in diseases such as asthma, but neither of these cytokines has chemokine properties." (PMID 19772569, 2009). "These IL-4 antagonists prevent the development of asthma in vivo in animal models." (PMID 18315837, 2008). "The 5q23.2-q34 region contains the cytokine gene cluster (IL4, Il13, IL5, IL12B) and has previously been suggested as an asthma/atopy susceptibility locus and the 7p21.1-14.1 region contains the previously identified asthma susceptibility gene, GPRA (7p14.3)." (PMID 18442398, 2008). "In a prior study, injections of IL-4 monoclonal antibody (mab) in OVA-sensitized and challenged mothers attenuated the maternal effect, implying that this cytokine played a significant mechanistic role in the maternal transfer of asthma risk." (PMID 17662138, 2007). "Because in a prior study, the maternal effect could be attenuated with a single injection of IL-4 mab, we postulated that IL-4 could also play a pivotal role in the maternal transmission of asthma in the TDI ACD group." (PMID 17662138, 2007).
asthma (continued). "We predicted that mothers who lacked IL-4 production would have decreased ability to transmit asthma risk to offspring." (PMID 17662138, 2007). "IL-4 and IL-13 are interesting targets for allergy and asthma therapies." (PMID 16640778, 2006). "Although murine immune system differ than human immune system, in general asthma and allergic disorders are casually characterized by elevated Th2 cytokines (IL-4, IL-5, IL-13) and the chronic inflammatory response in asthmatic airways is maintained by Th1 cytokines." (PMID 17034639, 2006). "In addition, the asthma patients had significantly higher concentrations of total IgE and IL-4 than the controls (p < 0.001 for all comparisons)." (PMID 15710045, 2005). "T helper type 2 cytokines including IL-4 have major role in asthma pathogenesis." (PMID 15907205, 2005). "Upregulation of CD23 in huASMC by IL-4 and GM-CSF can contribute to changes in huASMC and may provide an avenue for new therapeutic options in asthma targeting ASMC." (PMID 15907205, 2005). "Further studies to intervene the upregulation of CD23 expression by cytokines IL-4 and GM-CSF may open a new avenue to target smooth muscle hypertrophy, an important element of severe asthma." (PMID 15907205, 2005). "Similarly, the preventive activities of RosA in female BALB/c mice induced asthma demonstrated that pretreatment with RosA (5–20 mg/kg) 1 h prior to the OVA challenge significantly inhibited increases in Th2 cytokines (IL‐4, IL‐5, and IL‐13) and markedly reduced IgE concentrations in the BALF." (PMID 41523289, 2026). "The current biologics for severe asthma treatment include omalizumab (anti-IgE), mepolizumab and reslizumab (anti-IL-5), benralizumab (anti-IL-5 receptor), dupilumab (anti-IL-4 receptor α, blocking both the IL-4 and IL-13 pathways), and tezepelumab (anti-TSLP)." (PMID 40364184, 2025). "In patients with type-2 high asthma, the type-2 immune response is excessively activated, and T helper type-2 (Th2) cells and group 2 innate lymphoid cells (ILC2s) produce large amounts of the type-2 cytokines like interleukin-4 (IL-4), IL-5, IL-9, and IL-13, which in turn induce asthmatic features." (PMID 41322401, 2025). "However, studies in asthma and other inflammatory diseases suggest that genetic variations in cytokines such as IL-5, IL-4, IL-13, and TNF may influence responses to biologic therapies." (PMID 40149465, 2025). "Furthermore, no secretion of asthma-associated cytokines such as IL-4 or IL-13 was observed in response to hPIV-3 infection (data not shown)." (PMID 41239423, 2025). "The Th2 cytokines seen in asthma, especially IL-4 and IL-13, may downregulate the Th1 immune response, potentially offering a protective mechanism against COVID-19 and could provide an explanation as to why asthmatic patients infected with SARS-CoV-2 have better disease outcomes." (PMID 40004141, 2025). "Additionally, elevated Th2 cytokines such as IL-4 and IL-13 in poorly controlled asthma may upregulate IgE synthesis and mast cell activation, further compounding the risk of anaphylactic shock." (PMID 40917873, 2025). "In addition, in chronic asthma, Th2 cells are known to infiltrate the lungs and produce inflammatory cytokines, such as IL-4, IL-5, and IL-13, which are crucial in initiating and progressing allergic diseases, including asthma, by driving Th2-mediated immune responses." (PMID 40622480, 2025). "In particular, IL-4 is suggested to play an important role in early phase of asthma occurrence via positive loop to produce Th2 cell-related cytokines and IgE, but IL-13 is considered to relate with the late phase of asthma, such as mucous hypersecretion and airway remodeling." (PMID 40323927, 2025). "Significant improvements in FEV1 (MD, 0.11; 95% CI, 0.10 to 0.11), Asthma Control Questionnaire scores (MD, −0.20; 95% CI, −0.22 to −0.18), and annual exacerbation rates (MD, −0.15; 95% CI, −0.16 to −0.14) were also seen with anti–IL-4/IL-13 biologic therapies." (PMID 39844912, 2025).